MCL1 (MCL1 apoptosis regulator, BCL2 family member)
Diseases named in the same sentence as MCL1 in open-access papers (continued):
Sharing a sentence is not in itself a finding about the gene and the disease.
influenza (1 paper, 2025). An acute viral infection of the respiratory tract, occurring in isolated cases, in epidemics, or in pandemics; it is caused by serologically different strains of viruses (influenzaviruses) designated A, B, and C, has a 3-day incubation period, and usually lasts for 3 to 10 days. "Patients undergoing treatments targeting Mcl-1 could be more susceptible to severe RSV and influenza infection or other respiratory pathogens, due to the virus being able to replicate uncontrolled when Mcl-1 is suppressed." (PMID 40951311, 2025). "Given that Mcl-1 is often targeted in cancer therapy, we examined whether reducing Mcl-1 in human cells would have a similar effect on RSV and influenza." (PMID 40951311, 2025).
insulinoma (1 paper, 2019). "Experiments with MIN6 insulinoma beta cell line determined that miR-29 targets a member of the BCL2 family, an antiapoptotic protein, the MCL1 (myeloid cell leukemia 1) (MCL-1) gene." (PMID 31683538, 2019).
intracranial aneurysm (1 paper, 2021). "Furthermore, MCL1 contributes to vascular smooth muscle cell proliferation and inhibits apoptosis in vascular diseases, including intracranial aneurysm." (PMID 34109173, 2021). "Thus, we hypothesized circ_DOCK1 might indirectly regulate MCL1 by miR-409-3p to participate in the regulation of vascular smooth muscle cell dysfunction in intracranial aneurysm." (PMID 34109173, 2021). "This study proposed the importance of circ_DOCK1/miR-409-3p/MCL1 axis in regulating HBVSMC dysfunction and provided a potential therapeutic target for intracranial aneurysm treatment." (PMID 34109173, 2021).
invasive carcinoma (1 paper, 2016). A carcinoma that is not confined to the epithelium, and has spread to the surrounding stroma. "MCL-1 expression was detected in the cytoplasm and in the nucleus of invasive carcinoma cells, with some heterogeneity observed within tumors." (PMID 27931239, 2016).
kidney injury (1 paper, 2025). Trauma to the kidney. "In summary, our findings demonstrate that MCL-1 is a critical survival factor in senescent TEC during AAI-induced kidney injury and that its selective inhibition with UMI-77 provides therapeutic benefit, particularly when administered early." (PMID 41298369, 2025). "Based on these results, we define this previously uncharacterized cell population as MCL-1+ senescent TEC and propose MCL-1 as a promising target for selective senolytic intervention in AAI-induced kidney injury." (PMID 41298369, 2025).
latent infection (1 paper, 2017). "In our BH3 profiling study, we found that mature human peripheral blood B cells depend solely on BCL-2 for survival while EBV latent infection further suppressed apoptotic priming during outgrowth by initially upregulating MCL-1, followed by BFL-1." (PMID 28425914, 2017).
Legionella infection (1 paper, 2018). "Legionella infection also induces suppression of MCL1 expression." (PMID 30261081, 2018).
leprosy (1 paper, 2018). Leprosy is a chronic infectious disease affecting primarily the skin and peripheral nervous system. "Taken together, concerning miRNA regulation, our data suggest an antiapoptotic profile for leprosy in general, driven by BCL2, MCL1, and CASP8." (PMID 29593724, 2018).
leukodystrophy (1 paper, 2021). Leukodystrophies are a group of rare, progressive, metabolic, genetic diseases that affect the brain, spinal cord and often the peripheral nerves. "Our data show that oligodendrocytes require MCL-1 to suppress apoptosis, implicate MCL-1 deficiency in white matter pathology, and suggest apoptosis inhibition as a leukodystrophy therapy." (PMID 34873168, 2021). "The symptoms, white matter specificity, and early postnatal onset of the Mcl-1 deletion phenotype resembled clinical leukodystrophies observed in patients." (PMID 34873168, 2021). "We focused on this leukodystrophy model because MCL-1 abundance is known to depend on translational regulation and activation of the integrated stress response (ISR), and both translation and ISR activation are abnormal in eIF2B5R132H/R132H mice." (PMID 34873168, 2021). "Based on the similarity of the Mcl-1cKO phenotype to human leukodystrophies, we investigated whether MCL-1 expression is altered in the eIF2B5R132H/R132H mouse model of VWMD." (PMID 34873168, 2021). "To determine whether astrocytes in Mcl-1-deleted mice had increased NESTIN expression, as seen in these leukodystrophies, we compared NESTIN+/GFAP+ populations in P14 Mcl-1cKO mice and controls." (PMID 34873168, 2021).
Leukoencephalopathy (1 paper, 2021). This term describes abnormality of the white matter of the cerebrum resulting from damage to the myelin sheaths of nerve cells. "In contrast, Mcl-1-deleted mice with heterozygous co-deletion of Bax, with the genotype hGFAP-Cre/Mcl-1loxP/loxP/BaxloxP/+ (Mcl-1cKO/Baxfl/+), showed a progressive leukoencephalopathy phenotype similar Mcl-1cKO mice." (PMID 34873168, 2021).
lichen planus (1 paper, 2013). A chronic, recurrent, pruritic inflammatory disorder of unknown etiology that affects the skin and mucus membranes. "In those cases of lichen planus in which Bcl-2 was absent, Bax may have bound with other regulatory proteins, including other members of the Bcl-2–related family, such as Bcl-x, McL-1, Bad or Bak." (PMID 24551804, 2013).
malaria (1 paper, 2021). Malaria is a serious and sometimes fatal disease caused by a parasite that commonly infects a certain type of mosquito which feeds on humans. "Mcl-1, heat shock protein 27, and dihydroartemisinin, an anti-malaria drug, bind directly to TCTP and regulate its stability." (PMID 34675258, 2021).
malignant rhabdoid tumors (1 paper, 2021). "Additionally, combing LDC0000167 with the BRD4 inhibitors-JQ1 or iBET-762 against malignant rhabdoid tumors, down-regulated the anti-apoptotic genes MCL-1, BCL-6 and BTG1 as well as MYC and inhibited cell-proliferation and tumor growth in vitro and in vivo." (PMID 34062779, 2021).
myelofibrosis (1 paper, 2025). A partial or complete replacement of the bone marrow stroma by fibrous tissue. "Here, we evaluated baseline and on-treatment expression of BCL2, BCL2L1 (encoding BCL-xL), and MCL1 in 19 myelofibrosis patients receiving ruxolitinib." (PMID 41287119, 2025).
myocardial ischemia (1 paper, 2024). A disorder of cardiac function caused by insufficient blood flow to the muscle tissue of the heart. "In an animal model of myocardial ischemia/reperfusion, DEX alleviated myocardial mitochondrial apoptosis through a pathway involving the lncRNA HCP5/miR-29a/MCL1 axis and activation of Janus kinase 2/signal transducer and activator of transcription 3 signaling." (PMID 39881865, 2024).
nephritis (1 paper, 2023). Inflammation of renal tissue. "We have previously shown, using the same neutrophil-deficient mouse strain, that myeloid-specific Mcl1 is required in the nephrotoxic nephritis model." (PMID 36154801, 2023).
neuropathy (1 paper, 2024). A disorder affecting the nervous system that manifests with pain, tingling, numbness, and/or muscle weakness. "Chronic CHIKV patients also show upregulation of genes associated with neuronal death (FOXO3, MCL1, ZNF746, and PICALM) and T-cell differentiation, which may contribute to secondary neuropathy symptoms." (PMID 39596565, 2024).
non-alcoholic steatohepatitis (1 paper, 2021). "More recently, Mcl-1 deficiency in the liver was shown to exacerbate the non-alcoholic steatohepatitis (NASH) phenotype with progression to liver cirrhosis and/or liver tumor in an obesity induced NASH model." (PMID 34336857, 2021).
oral cavity cancer (1 paper, 2022). A primary or metastatic malignant neoplasm involving the oral cavity. "Mcl-1 expression was associated with the progression of oral cavity cancers." (PMID 35524332, 2022). "The molecular mechanism and pathways of Mcl-1 in oral cavity cancers established via experimental results have been highlighted in this review." (PMID 35524332, 2022). "In this paper, we attempted to review the expression, function, molecular mechanism and pathway, and therapeutic approach of Mcl-1 in oral cavity cancers." (PMID 35524332, 2022).
oropharyngeal cancer (1 paper, 2012). Carcinoma, predominantly squamous cell, arising from the epithelial cells of the oropharynx. "Our results suggested that polymorphisms of NOXA and MCL1 may modify the risk of HPV16-associated oropharyngeal cancer." (PMID 22548841, 2012). "In consistence with this scenario, we found in current study that, to some extent, the risk of HPV16-associated SCCHN, particular oropharyngeal cancer, can be modified by genetic variants of NOXA and MCL1." (PMID 22548841, 2012). "We found that putatively functional polymorphisms of NOXA and MCL1 may modify the risk of SCCHN associated with HPV seropositive, especially the risk of oropharyngeal cancer among never smokers, never drinkers and younger individuals." (PMID 22548841, 2012).
osteoporosis (1 paper, 2024). A condition of reduced bone mass, with decreased cortical thickness and a decrease in the number and size of the trabeculae of cancellous bone (but normal chemical composition), resulting in increased fracture incidence. "Since VK2 (GlakayR) itself is nontoxic and has been administered daily for a long time to patients with osteoporosis in Japan, the use of VK2 as a chemosensitizer for VEN via NOXA-mediated MCL-1 suppression appears to be a promising strategy." (PMID 39052583, 2024).
ovarian adenocarcinoma (1 paper, 2019). An adenocarcinoma that arises from the ovary. "It has been reported that linc00152 might directly bind to miR-125b, up-regulate Mcl-1 (myeloid cell leukemia-1), and protect ovarian adenocarcinoma cells from apoptosis." (PMID 31896236, 2019).
ovarian disorder (1 paper, 2021). A disease involving the ovary. "MCL1 has been found to be involved in the development of ovarian disorders in multiple ways, such as by deubiquitinating and interacting with miRNAs." (PMID 34413875, 2021).
parasite infection (1 paper, 2023). "During parasite infection, TCTP safeguards Mcl-1 from degradation by the E3 ubiquitin ligase Mule across multiple cell lines." (PMID 37201583, 2023).
peanut allergy (1 paper, 2025). "While the role of most of these genes in peanut allergy has not been investigated, overexpression of myeloid cell leukemia‐1 (MCL‐1) protects eosinophils from apoptosis and exacerbates allergic inflammation." (PMID 40693699, 2025).
placental insufficiency (1 paper, 2021). Failure of the placenta to deliver an adequate supply of nutrients and oxygen to the fetus.
polycythemia vera (1 paper, 2025). "HHT, a recognized protein synthesis inhibitor, playing a significant role in the treatment of hematological diseases such as AML, CML, MDS, and polycythemia vera by regulating mechanisms including KIT, MYC, MCL-1 and Cyclin-D1." (PMID 40591114, 2025).
pulmonary fibrosis (1 paper, 2024). Chronic progressive interstitial lung disorder characterized by the replacement of the lung tissue by connective tissue, leading to progressive dyspnea, respiratory failure, or right heart failure. "We speculate that the mechanism of MCL-1 and BCL2A1 participating in promoting pulmonary fibrosis is related to apoptosis resistance." (PMID 38609879, 2024).
SARS-CoV infection (1 paper, 2021). "Regarding the human coronaviruses, ex-vivo experiments have demonstrated that upon SARS-CoV infection, viral 7a protein directly interacts and forms a complex with antiapoptotic Bcl-XL protein and other prosurvival factors (Bcl-2, Mcl-1, and A1), promoting apoptosis in a caspase-3 dependent manner." (PMID 33652685, 2021).
schizophrenia (1 paper, 2026). A major psychotic disorder characterized by abnormalities in the perception or expression of reality.
septic arthritis (1 paper, 2013). "In the current paper, we documented the elevated level of Mcl-1 in S. aureus-infected human primary macrophages and joints in murine model of septic arthritis, associated with infiltration of macrophages into the synovia." (PMID 23431241, 2013). "The confirmation of Mcl-1 role in staphylococcal infection was obtained studying S. aureus-induced septic arthritis." (PMID 23431241, 2013).
staphylococcal infection (1 paper, 2013). An infection caused by Staphylococcus. "Moreover, the upregulation of Mcl-1 in vivo indicates that observed phenomenon plays a role during staphylococcal infection." (PMID 23431241, 2013).
staphylococcus aureus infection (1 paper, 2025). An infectious process in which the bacteria Staphylococcus aureus is present. "Staphylococcus aureus infection is associated with increased macrophage expression of anti-apoptotic MCL1, and failure of apoptosis-associated bacterial killing, which normally provides a default clearance mechanism for other pathogens when phagolysosomal killing has been exhausted." (PMID 40447280, 2025).
status epilepticus (1 paper, 2013). Status epilepticus is defined as a continuous seizure lasting more than 30 min, or two or more seizures without full recovery of consciousness between any of them. "Chemoconvulsive thresholds and/or status epilepticus were found to be altered in mice lacking Bak, Mcl-1, Bcl-w and Bad, whereas loss of Bim, Bid, Puma and Bmf does not affect evoked seizures." (PMID 23882182, 2013). "A neuroprotective role for Mcl-1 was supported by the finding that heterozygous mice (Mcl1+/−) (knockout is embryonic lethal) displayed a four-fold increase in seizure-induced neuronal death following pilocarpine-induced status epilepticus." (PMID 23882182, 2013).
thymic epithelial tumor (1 paper, 2023). "MCL1 is essential for the maintenance of cortical and medullary thymic epithelial cells, suggesting its potential relevance in thymic epithelial tumor development." (PMID 38201593, 2023). "Survival of thymic epithelial tumor cell lines (T1889, T1682, and TY82) depends on BCL2 and MCL1 expression, as demonstrated by siRNA knockdown." (PMID 38201593, 2023).
trauma (1 paper, 2025). "In keeping with this theory, and in line with previous reports, we found that culturing neutrophils isolated from HCs in media supplemented with serum isolated from trauma patients significantly reduced their rate of spontaneous apoptosis and delayed the turnover of Mcl-1." (PMID 40422258, 2025).
vasculitis (1 paper, 2023). "The aim of the current study was first to assess if myeloid-specific Mcl1 was required in murine anti-MPO vasculitis." (PMID 36154801, 2023). "Here, we assessed if myeloid-specific Mcl1 was required in murine anti-myeloperoxidase vasculitis and whether inhibition of myeloperoxidase was protective." (PMID 36154801, 2023). "Thus, our results show that while myeloid-specific Mcl1 is required in this model of anti-myeloperoxidase vasculitis, myeloperoxidase inhibition is not protective." (PMID 36154801, 2023).
vitiligo (1 paper, 2021). Generalized well circumscribed patches of leukoderma that are generally distributed over symmetric body locations and is due to autoimmune destruction of melanocytes. "Research has proposed that MCL1 is involved in inducing synergistic inhibitory effects on Fas-mediated apoptosis in model vitiligo model." (PMID 33977869, 2021).
Wilms' Tumour (1 paper, 2010). "For example, MCL1 has been found to support cell survival in Wilms' Tumour cell lines." (PMID 20976140, 2010).